IGF1 (insulin like growth factor 1)
Diseases named in the same sentence as IGF1 in open-access papers (continued):
Sharing a sentence is not in itself a finding about the gene and the disease.
acute lymphoblastic leukemia (9 papers, 2002 to 2024). Leukemia with an acute onset, characterized by the presence of lymphoblasts in the bone marrow and the peripheral blood. "The apparent association between high birth weight and increased risk of acute lymphoblastic leukaemia (ALL) has stimulated research into the role of insulin growth factor-1 (IGF-1) and relevant receptors in abnormal haematopoiesis." (PMID 11875699, 2002). "The finding of overall reduced IGF-1 levels in the children before chemotherapy treatment is in line with previous findings of low IGF-1 levels at diagnosis in children with acute lymphoblastic leukemia and in children with benign hematological diseases." (PMID 32793242, 2020). "•Dual insulin-like growth factor 1 receptor (IGF1/R) + mitogen-activated protein kinase/extracellular signal-regulated kinase (ERK) kinase (MEK) inhibition synergistically sensitize apoptosis-resistant acute lymphoblastic leukemia (ALL) cells." (PMID 29656114, 2018).
amyloidosis (9 papers, 2021 to 2025). A disorder characterized by the localized or diffuse accumulation of amyloid protein in various anatomic sites. "Studies in mouse models have shown that reduced IGF-1 signaling via Igf1r haploinsufficiency reduces disease burden in models of amyloidosis." (PMID 41402425, 2025). "In this regard, compared to the amyloid group, rats that underwent treadmill exercise for 4 weeks in addition to intranasal insulin pretreatment and therapy showed higher levels of IGF1, BDNF, and GLUT4 gene expression in the hypothalamus." (PMID 38987609, 2024). "Considering that cGP regulates IGF-1 activity, it is possible that the effects of cGP observed in this study on memory and amyloid plaque load involve, at least in part, IGF-1 signaling." (PMID 36909366, 2023). "The dramatic increase of the IGF-1 after amyloid exposure is probably a “cry to survive” compensatory response to brain damage, as an attempt to preserve neurons that are still intact and/or have the potential for survival." (PMID 34209299, 2021). "The concentration of IGF-1 increased after PEG injection in the hypothalamus in comparison with the amyloid group." (PMID 34209299, 2021). "The concentration of IGF-1 significantly elevated in the cerebral cortex, hippocampus and hypothalamus after amyloid exposure." (PMID 34209299, 2021). "Many studies have suggested that IGF-1 exacerbates amyloid pathologies." (PMID 36755922, 2023). "In AD, elevated levels of tumor necrosis factor-α (TNF-α) may play a significant role in exacerbating amyloidosis, and IGF-1 attenuate amyloidosis by antagonizing TNF-α." (PMID 36691085, 2023).
atrial fibrillation (9 papers, 2019 to 2023). A disorder characterized by an electrocardiographic finding of a supraventricular arrhythmia characterized by the replacement of consistent P waves by rapid oscillations or fibrillatory waves that vary in size, shape and timing and are accompanied by an irregular ventricular response. "It has been shown that BGP-15-treatment reduces the incidence of atrial fibrillation (AF) episodes in a transgenic mouse model of HF, and this effect has been associated with the increased phosphorylation of the cardiac-specific insulin-like growth factor 1 (IGF1) receptor." (PMID 36986459, 2023). "Multivariable Cox regression showed that IGF-1 levels, IGFBP-1 levels, and IGFBP-1/IGF-1 ratio were not predictive of prognosis after adjusting for age, gender, atrial fibrillation, and NT-proBNP in patients with HF." (PMID 35127852, 2021).
End Stage Liver Disease (9 papers, 2012 to 2025). Final stage of a liver disease when the liver failure is irreversible and LIVER TRANSPLANTATION is needed. "In aging or end-stage liver disease, hepatic dysfunction, along with a reduction in growth hormone (GH) receptors, leads to decreased serum levels of insulin-like growth factor 1 (IGF-1)." (PMID 40951438, 2025). "A study on children with end-stage liver disease showed that low BMD was associated with low serum IGF-1 levels and liver transplantation led to significant improvement in serum IGF-1 levels and BMD." (PMID 36010307, 2022). "The dramatic metabolic change represented by LT leads to a complete recovery of the GH/IGF-1 axis in adult and pediatric patients with end-stage liver disease." (PMID 26186540, 2015). "They found that lower plasma IGF-1 and higher plasma VEGF levels significantly correlated with advanced end-stage liver disease and HCC clinicopathologic parameters and poor overall survival; with cut-off values of 26 ng/mL and 450 pg/mL, respectively." (PMID 25013622, 2012).
goiter (9 papers, 2012 to 2025). Enlargement of the thyroid gland usually caused by lack of iodine in the diet, hyperthyroidism, or thyroid nodules. "It has been previously demonstrated that IGF-1 plays a role in goiter growth, with its signaling thought to stimulate proliferation and impair apoptotic functions." (PMID 41373986, 2025). "Long-lasting stimulation of the follicular epithelium by GH and IGF-1 can lead to an increase in thyroid volume and the development of goiter." (PMID 36945936, 2023). "Goiter is described in 25 to 90% of the acromegalics, multinodular goiter in 65%, and there is a positive correlation between thyroid volume and GH and IGF-1 levels." (PMID 33292786, 2020). "In addition, to explain the effects of IGF-1 in the thyroid tissue, the prevalence of goiter in pygmies who has low IGF-1 levels is low, although the lack of advanced iodine is apparent." (PMID 29081797, 2017). "Children with goiter were found to have higher levels of IGF-1." (PMID 29081797, 2017). "A study on children with simple goiter showed that serum IGF-1 levels in children with goiter were lower than those children without goiter, reflecting that low-levels of IGF-1 in serum may be associated with thyroid enlargement." (PMID 31077177, 2019).
influenza (9 papers, 2016 to 2024). An acute viral infection of the respiratory tract, occurring in isolated cases, in epidemics, or in pandemics; it is caused by serologically different strains of viruses (influenzaviruses) designated A, B, and C, has a 3-day incubation period, and usually lasts for 3 to 10 days. "Likewise, IGF1 was identified in association with the risk to develop neuropsychiatric and neurodevelopmental disorders due to maternal immune activation secondary to influenza infection." (PMID 33834688, 2021). "However, whether IGF1 plays a significant role in mediating inflammation and pathology during influenza infection and its associated mechanism remains unknown." (PMID 31849847, 2019). "The risk gene PPP2R5A is mainly involved in Influenza Infection, protein localization to membrane, PID IGF1 PATHWAY, CTLA4 inhibitory signaling, Platelet activation, signaling and aggregation, and Hemostasis." (PMID 33014188, 2020). "Overexpression of IGF1 aggravated cytokine expression during infection by influenza, while blocking of IGF1 production in mice treated with IGF1R inhibitor, decreased immunopathology." (PMID 31849847, 2019). "IGF1 overexpression aggravated influenza-mediated inflammatory responses, whereas the inhibition of IGF1 expression reduced such inflammatory responses." (PMID 31849847, 2019). "Another metabolic hormone, IGF-1, directly impacts vaccine efficacy, as shown in a mouse model of macrophage-specific IGF-1 deficiency (Igf1fl/fl:Lyz2.Cre), which exhibited a significant reduction of antigen-specific IgG titres following influenza vaccination." (PMID 37330692, 2023). "IGF1 may provide a therapeutic target for humans in response to an influenza outbreak, and inhibition of IGF1 or IGF1 receptor may represent a novel approach to influenza treatment." (PMID 31849847, 2019). "Thus, inhibiting IGF1 or IGF1R expression to block downstream signaling may be a novel treatment strategy for influenza infection." (PMID 31849847, 2019). "Thus, IGF1 could regulate influenza virus-mediated acute inflammatory lung injury, which may provide a therapeutic target for humans in response to an influenza outbreak." (PMID 31849847, 2019). "Studies in mice revealed that IGF-1 treatment induced higher antibody levels, and in the absence of macrophage-derived IGF-1, the antibody titers elicited by subunit influenza vaccine were lower than in the wild-type condition." (PMID 38005994, 2023). "However, the viral load of the PR8 + PPP group and the PR8 + PBS group was similar, indicating that IGF1 responded to influenza infection via the host immune response rather than targeting viral replication." (PMID 31849847, 2019). "Thus, the inhibition of IGF1, rather than antiviral pathways that affect viral replication, may provide a new therapeutic avenue for influenza that limits detrimental inflammatory responses to infection." (PMID 31849847, 2019).
invasive breast carcinoma (9 papers, 2006 to 2023). A carcinoma that infiltrates the breast parenchyma. "We, therefore, investigated the associations between serum concentrations of testosterone, sex hormone-binding globulin (SHBG) and IGF-1 and the risk of invasive breast cancer in pre- and post-menopausal women in UK Biobank." (PMID 33864017, 2021). "In this study, higher concentrations of circulating IGF1 were significantly and independently associated with a lower risk of all-cause mortality in women with invasive breast cancer." (PMID 32974138, 2020). "In this large prospective study, circulating IGF1 was inversely and independently associated with all-cause mortality in invasive breast cancer patients, and this association was consistent among patients with different strata of insulin and clinical characteristics." (PMID 32974138, 2020). "Overall, the findings from this large prospective cohort study confirm significant associations of testosterone, IGF-1 and SHBG with the risk of invasive breast cancer, with evidence of heterogeneity by menopausal status for testosterone." (PMID 33864017, 2021). "In this study, involving about 160,000 women, there were significant associations of testosterone, IGF-1 and SHBG with the risk of invasive breast cancer, with evidence of heterogeneity observed by menopausal status for testosterone." (PMID 33864017, 2021). "Taken together, our findings indicate that IGF-1 and 2 are highly expressed by both macrophages and fibroblasts in invasive breast cancer, and that blockade of IGF potentiates the efficacy of paclitaxel." (PMID 29367764, 2018). "Additionally, we found that high circulating IGF-1 was a contributor to the occurrence of in-situ breast cancer and invasive breast cancer." (PMID 38000092, 2023). "Among the 11 hematological and biochemical biomarkers found to be associated with the risk of invasive breast cancer, some were inflammatory markers, such as white blood cell count, neutrophil count, and CRP, while others were endogenous hormones, such as SHBG, IGF-1, and testosterone." (PMID 38000092, 2023). "Here we show that IGF-1 and 2 are secreted by macrophages and fibroblasts, both at the primary site and metastatic site in invasive breast cancer, and that blocking IGF increases the efficacy of paclitaxel, a chemotherapeutic agent commonly used for the treatment of invasive breast cancer." (PMID 29367764, 2018). "First, we analyzed correlation between PRCP gene expression and IGF1 (IGF1R ligand) and NRG1 (HER3 ligand) expression in 1093 cases of invasive breast cancer (TCGA database) using TIMER software." (PMID 36332175, 2022). "Together, these findings provide evidence that macrophages and fibroblasts are the main sources of IGF-1 and IGF-2 both at the primary and the metastatic site in invasive breast cancer." (PMID 29367764, 2018).
juvenile idiopathic arthritis (9 papers, 2014 to 2025). Juvenile idiopathic arthritis (JIA) is the term used to describe a group of inflammatory articular disorders of unknown cause that begin before the age of 16 and last over 6 weeks. "Several rheumatic diseases are characterized by abnormalities in the GH/IGF-1 paracrine axis, and although in adults the relationship between serum GH levels and disease progression is debated, juvenile chronic arthritis patients have reduced GH levels." (PMID 29887869, 2018). "Decreased IGF-1 levels are common in juvenile idiopathic arthritis (JIA), but whether IGF-1 is related to sex and differ during the pathogenic progress of JIA is unknown." (PMID 30622975, 2018). "The decreased plasma level may be caused by proteolytic degradation of IGF-1 binding protein-3 resulting in an increased clearance of IGF-1, as previously shown in a model of juvenile arthritis induced by IL-6 overexpression." (PMID 35388142, 2022). "In juvenile idiopathic arthritis (JIA), a similar trend of reduced serum IGF-1 or Insulin-Like Growth Factor Binding Protein 3 (IGFBP-3) levels in patients compared to controls was observed." (PMID 41383600, 2025).
kidney cancer (9 papers, 2008 to 2023). Primary or metastatic malignant neoplasm involving the kidney. "Higher IGF-1 has been reported to be modestly associated with increased risk of overall cancer risk, including kidney cancer based on a cohort study analysis from the UK Biobank." (PMID 37346909, 2023).
male infertility (9 papers, 2009 to 2024). The inability of the male to effect fertilization of an ovum after a specified period of unprotected intercourse. "Research on IGF-1 is clinically and translationally significant as it offers potential solutions to male infertility and other reproductive diseases." (PMID 38792459, 2024). "Research on IGF-1 in the male reproductive system not only enhances our understanding of male fertility and reproductive health but also offers potential therapeutic avenues for addressing male infertility and reproductive disorders." (PMID 38792459, 2024). "Insulin-like growth factor-1 (IGF-1) is related to male infertility." (PMID 35739906, 2022). "IGF-1 is a potent mitogenic, anabolic substance, and regulator of male infertility." (PMID 34566323, 2021). "The understanding of the role of IGF1 and its receptor on human SC physiology, as well as the possible influence on FSH effects, might help to elucidate some cases of unexplained male infertility." (PMID 31035547, 2019).
Myocardial fibrosis (9 papers, 2019 to 2025). "Reduced levels of IGF-1 are associated with higher circulating levels of growth hormone and insulin that promote hypertrophy and myocardial fibrosis." (PMID 32033349, 2020). "In addition, one-time skeletal muscle injection of adeno-associated virus 5 encoding IGF-1 in coronary occlusion heart failure rat model significantly reduced not only cardiomyocyte apoptosis but myocardial fibrosis." (PMID 34244467, 2021). "In conclusion, the IC injection of 5 × 106 IGF-1 loaded MSPs in a porcine acute MI model successfully improves cardiac function and limits myocardial fibrosis, which could be clinically relevant." (PMID 32346015, 2020). "MiR-29 is decreased in kidney, lung, liver, and myocardial fibrosis and it is important to fibrosis molecules, such as collagen I and III, insulin-like-growth factor-1 (IGF-1), and connective tissue growth factor (CTGF)." (PMID 38157020, 2023).
ovarian failure (9 papers, 2010 to 2024). "Despite these mentioned studies, no reports explored the potential protective effects of these essential oils against radiotherapy-induced ovarian failure or linked their radioprotection in ovaries with the serum IGF-1 levels." (PMID 31531182, 2019). "The present study investigated the mechanisms of the potential radioprotective effect of growth hormone (GH) on γ irradiation-induced ovarian failure and the impact of the insulin like growth factor 1 (IGF-1) in the underlying protection." (PMID 26465611, 2015). "We report a case of a 45-year-old caucasian woman with early ovarian failure for 2 years and amenorrhea since the age of 43, who presented with Adult Growth Hormone Deficiency and an IGF-1 of 126 ng/mL." (PMID 20843352, 2010). "We report on a case where a woman with early ovarian failure, accompanied by seemingly low IGF-1 plasma levels, had severe comorbid symptoms which worsened as her IGF-1 levels continued to fall independent of anterior pituitary hormone deficiency assessment." (PMID 20843352, 2010). "Therefore, the aim of the present study was to explore the modulatory effects of CAR or thymol on radiation-induced POF in vivo as well as the possible underlying mechanisms, particularly the impact on the cross-talk between TNF-α and IGF-1 signaling in irradiation-induced ovarian failure." (PMID 31531182, 2019).
pancreatic ductal adenocarcinoma (9 papers, 2010 to 2026). An infiltrating adenocarcinoma that arises from the epithelial cells of the pancreas. "Further research on these findings suggests that an increased risk of pancreatic ductal adenocarcinoma may be linked to high IGF-1/low IGFBP-3 serum concentrations." (PMID 37623681, 2023). "However, a previous study showed that let-7 family regulated the expression of components of the INSR/IGF1 pathway in individuals with pancreatic ductal adenocarcinoma." (PMID 37958657, 2023). "IGF-1 and insulin-like growth factor 1 receptor (IGF-1R) have been reported to be abundantly expressed in pancreatic ductal adenocarcinoma tissue." (PMID 37623681, 2023). "Patients with pancreatic ductal adenocarcinoma were shown to have excessive levels of IGFBP-1, 3, IGF2BP-2, IGF-1, and IGF1R in their blood and pancreatic cells." (PMID 37623681, 2023).
Phelan-McDermid syndrome (9 papers, 2014 to 2024). A rare genetic neurodevelopmental disorder characterized by neonatal hypotonia, global developmental delay, normal to accelerated growth, absent to severely delayed speech, and minor dysmorphic features. "In recent years, neurologic and other effects in Phelan McDermid Syndrome have been studied after IGF-1, but not after hrGH therapy." (PMID 34777208, 2021).
pituitary (9 papers, 2015 to 2026). "Peripheral hospitals carried out serum IGF-1 measurements, unless patients developed symptoms suggestive of GH deficiency despite receiving optimal treatment for other pituitary hormone deficiencies as necessary." (PMID 34112169, 2021). "An extended thyroid panel with insulin-like growth factor-1 analysis supported a diagnosis of hypophysitis." (PMID 28241874, 2017). "At age 11y, bone age study assessed a delay of 1 year; magnetic resonance imaging showed the hypophysis was reduced in size compared to age; low vitamin D and normal IGF1 values were recorded." (PMID 27717396, 2016). "Admittedly, the one case that proved to have a pituitary enlargement despite an IGF-1<1000 ng/ml had an IGF-1 very close to this cut-off (986 ng/ml)." (PMID 26023776, 2015). "However, FSH and IGF-1 co-association stimulates GLUT-1 expression at both protein and mRNA levels, suggesting that VitE indirectly enhances hypophysis endocrine status and ultimately provokes follicular cells proliferation/development by enhancing the GLUT-1 expression." (PMID 27482357, 2016).